NGF (nerve growth factor)
Diseases named in the same sentence as NGF in open-access papers (continued):
Sharing a sentence is not in itself a finding about the gene and the disease.
tumor (continued). "Nerve growth factor-siRNA might be one good option for OESCC treatment once tumour-specific siRNA delivering systems become available." (PMID 16832412, 2006). "Similar mechanisms promoting tumoral cell survival or counteracting neuronal differentiation may be also involved in NB where NGF/TrkA interaction induced differentiation of tumour cells." (PMID 11857022, 2002). "In addition to their effects on immune cells, tumor-derived neuropeptides interact with neurotrophic factors such as Nerve Growth Factor (NGF) and Brain-Derived Neurotrophic Factor (BDNF), which are critical for axonogenesis and nerve recruitment inside the TME." (PMID 40805163, 2025). "Similarly, NGF is synthesized in tumor cells in the form of proNGF." (PMID 38667297, 2024). "In the context of GBM, the most studied neurotrophins are NGF and NT-3, whose interaction with its specific receptor present on the surface of tumor cells, Tropomyosin-related kinase A and C (TrkA) (TrkC), respectively, could contribute to tumor aggressiveness." (PMID 39682125, 2024). "Understanding the intricate interactions of NGF with various cell types and pathways is crucial for developing targeted therapies that can modulate its effects in different disease contexts, offering a potential therapeutic strategy to inhibit tumor progression and improve patient outcomes." (PMID 38392180, 2024). "Thus, it is not surprising that NGF concentration in tumor tissue is associated with an increased metastasis rate and increased probability of R1 resection." (PMID 37834436, 2023). "Interestingly, in a genetic mouse line, where an excess amount of NGF is secreted by gastric epithelial cells, the stromal compartment of the lamina propria is significantly expanded, epithelial tissue architecture changes, and tumours arise." (PMID 35269454, 2022). "CAFs also cause tumour cells to secrete factors that stimulate them, such as hepatocyte growth factor (HGF), connective tissue growth factor (CTGF), epidermal growth factor (EGF), insulin-like growth factor (IGF), nerve growth factor (NGF), FGF, and Wnt family members." (PMID 36555218, 2022). "NGF is also produced in PDAC cells and might be secreted by tumour-associated immune cells." (PMID 36497277, 2022). "Thus, once released by TNBC cells, NGF might play a role in the autonomic innervation of the tumor and its aggressiveness." (PMID 34268306, 2021). "Additionally, metformin treatment of EOC cells increased the levels of miR-145 and miR-23b by blocking the NGF-induced decrease in these miRs, suggesting that the anti-tumour effects of metformin could be mediated by miR regulation." (PMID 33081077, 2020). "Acidosis, which is caused mainly by tumor cells and osteoclasts, activates the channels (TRPV1, ASICS3) and stimulates stromal cells to produce and release not only growth factors (e.g., NGF, brain-derived neurotrophic factor (BDNF)) but also pro-inflammatory mediators (e.g., IL1β, IL6, IL15, CCL5)." (PMID 31801267, 2019). "Indeed, heme is involved in the regulation of gene expression in neurons via nerve growth factor (NGF) signaling, thus suggesting that heme may modulate nerve outgrowth in the tumor microenvironment." (PMID 32010627, 2019). "When the inoculated mice were treated with NGF, reduction of tumor volume was accompanied by an increase in the number of giant multinucleated cells and areas of unstructured necrotic detritus, as well as by germination of muscle fibers and the presence of large blood vessels in tumor tissue." (PMID 28878143, 2017). "Interestingly, prostate cancer cells do not express NGF, suggesting that their implantation into the bone causes a tumour-associated effect on stromal cells." (PMID 28845385, 2017). "As observed after topical administration, exogenous NGF can arrest tumor cell proliferation in human ocular glioma, prompting to the hypothesis of an inhibitory rather than promoting NGF effect on cancer cell (stimulation and tumor progression)." (PMID 27439311, 2016).
tumor (continued). "In addition, NGF stimulated the expression of MMPs in tumor cells." (PMID 18983683, 2008). "We also performed semiquantitative RT–PCR for TrkA and p75NTR as well as NGF, which revealed that NGF and TrkA were expressed higher in the tumour portion than normal epithelium in 89 and 84% of patients, respectively, whereas p75NTR expression was lower in the tumour portion in 42% of patients." (PMID 16832412, 2006). "Macrophage- and lymphocyte-derived NGF and BDNF establish positive feedforward loops that amplify tumor-neural-immune interactions." (PMID 42212159, 2026). "Studies have shown that SCs can specifically activate receptor tyrosine kinase family members on the surface of tumor cells (including the RET, TrkA, TrkB) by secreting GDNF, NGF, and BDNF." (PMID 41583906, 2026). "Tumor growth can be mediated by stem cell factor (SCF), nerve growth factor (NGF), and platelet-derived growth factor (PDGF)." (PMID 41596472, 2026). "For instance, in vitro and in vivo, SCs supported the proliferation and migration of colon cancer cells by secreting NGF and activating the TrkA/ERK/ELK1/ZEB1 signaling pathway in tumor cells or via the activated NF-κB/IL-8 axis." (PMID 40940747, 2025). "Immunohistochemistry or multiplex immunofluorescence for NGF, BDNF, TrkA, TrkB, and phospho−Trk can be quantified by digital image analysis across tumor, stromal, and endothelial compartments." (PMID 41383615, 2025). "We found that in both metabolism-related pathways, SLC5A3 + tumor cells exhibit significant communication with CAFs, particularly through the FN1/SDC2, FGF7/FGFR1, NGF/SORT1, and LRPAP1/LRP1 receptor-ligand pairs." (PMID 40652057, 2025). "In preclinical models of cervical and breast cancer, anti-NGF antibodies and the Trk tyrosine kinase inhibitor GNF-5837 have demonstrated promising anti-tumor efficacy, though further clinical validation is needed to establish therapeutic relevance." (PMID 41163091, 2025). "A similar result was found for NGF, with a statistically significant result in the GSE26713 dataset, in which its expression was higher in healthy medullary tissue compared to tumor tissue at diagnosis." (PMID 40427122, 2025). "Neuronal secretions—including NGF, BDNF, CGRP, norepinephrine, and neuronal substance P—serve as potent mediators of tumor–nerve interactions." (PMID 41009819, 2025). "NGF can promote the expression of VEGF and indirectly affect the blood supply of the tumour, thus influencing its growth and metastasis." (PMID 40860871, 2025). "NGF activates TrkA receptors, promoting angiogenesis, epithelial‐mesenchymal transition (EMT), and tumor invasiveness, although its role can be context‐dependent, acting as either pro‐oncogenic or pro‐apoptotic." (PMID 40981722, 2025). "Superfluous NGF in TME influences the biological behaviour of cancer cells (e.g., tropism and proliferation), which is called tumour neurotrophic activity." (PMID 40783715, 2025). "Neurotrophic factors, including NGF and GDNF, are critical mediators of tumor innervation, playing a pivotal role in recruiting nerves and promoting neurogenesis within the TME." (PMID 41009819, 2025). "Moreover, the lower responsiveness to NGF in cSCC cells, despite preserved TrkA expression, supports the concept of a constitutively active or autocrine TrkA signaling loop that may contribute to tumor maintenance." (PMID 41226473, 2025). "Typically, NGF increases VEGF secretion by BC cells, which in turn increases the nerve and vascular density in tumour lesions." (PMID 40783715, 2025). "Hence, it could be used as an NGF inhibitor for pain relief and to control tumor progression." (PMID 39099944, 2024). "Conversely, it was also shown that NGF can also inhibit the growth of HT1080 fibrosarcomas or HepG2 tumors via its effects on innervation and maturation of tumor neovasculature, which regulates blood flow into tumor tissues." (PMID 38375479, 2024).
tumor (continued). "Mounting evidence suggests that malignant cells influence the tumor microenvironment (TME) by releasing a plethora of neurotrophic factors, e.g. NGF, BDNF, GDNF, Neuturin and Ephrin B1 to promote axonogenesis, neurogenesis and neural reprogramming." (PMID 39592661, 2024). "Main mast cells mediators have been described in the tumor microenvironment, including chymase, tryptase, VEGF, Histamine, TNF-α, MMP2, MMP-9, TIMPs, NGF, and sphingosine-1-phosphate." (PMID 38969910, 2024). "In order to better understand the molecular regulation mechanism and biological functioning of NGF and NGFR in tumor tissues, GSEA was performed using the pan‐cancer approach." (PMID 38204220, 2024). "For example, MCs release FGF-2, NGF, PDGF, VEGF, IL-8, and IL-10, which promote the expansion of tumor cells." (PMID 38233752, 2024). "NGF can affect the behavior of various cells within the TME, including immune cells, fibroblasts, and endothelial cells within the tumor, which can create an environment that supports CSC survival and function." (PMID 38392180, 2024). "We verified that LEP, NGF and PCOLCE2 were highly expressed in tumor tissues using COAD clinical samples." (PMID 38694509, 2024). "These factors, via the NGF-TRKA and ANAX2-SEMA3D-PLXND1 signaling axes, respectively, enhance the bidirectional chemotaxis between nerves and tumor cells, bringing them in closer proximity." (PMID 38567163, 2024). "Tumor growth (evaluated by the spreading area of LN229 implantedcells), tumor weight, and vascularization of the entire CAM significantlydecreased after VLO5 treatment, in contrast to NGF treatment." (PMID 39285908, 2024). "Research shows that cancer cells express neurotrophic markers such as NGF, GDNF, and brain‐derived neurotrophic factor (BDNF), releasing axon‐guiding molecules that promote axonogenesis and attract nerves to the tumor site." (PMID 39492832, 2024). "Consistently, the downregulation of NGF and NGFR in the tumor tissue of HCC patients was observed in the qRT‐PCR analysis and western blotting as well." (PMID 38204220, 2024). "The expression levels of LEP, NGF and PCOLCE2 proteins in tumor tissues were significantly increased compared with adjacent tissues." (PMID 38694509, 2024). "NGF‐NGFR communication was correlated positively with PD‐1/PDL‐1 and exhibited synergistic action with PD‐1 mAb‐suppressed tumor progression in both mouse models and patients." (PMID 38204220, 2024). "In oral and salivary cancers, NGF was shown to induce EMT, cell dispersion, and PNI, resulting in increased tumor aggressiveness via the activation of the PI3K/Akt signaling pathway." (PMID 39906323, 2024). "A recent study found that nerve‐derived NGF induces EMT and confers tumor cell resistance to the EGFR inhibitor erlotinib in HNSCC." (PMID 36039037, 2023). "Nerve growth factor (NGF) and its precursor proNGF are increasingly recognized as stimulators of human tumor progression." (PMID 36675126, 2023). "Anti-NGF treatment significantly reduced the density of nerve fibers, the formation of neuroma-like structures, the frequency of CIBP, and the generation of tumor-induced nociceptive behavior." (PMID 37007073, 2023). "Cancer cells can produce growth factors, such as nerve growth factor (NGF), and stimulate the growth of new axons into the tumor." (PMID 37371563, 2023). "Conversely, mediators released by mast cells such as FGF-2, NGF, PDGF, VEGF, IL-8, and IL-10 can promote the expansion of tumor cells." (PMID 36793597, 2023). "Factors such as IL-8, VEGF, PDGF, NGF, SCF, and histamine promote tumor growth, while IL-1, IL-6, TNF-α, and fibroblast proteases inhibit tumor growth." (PMID 37686677, 2023).
tumor (continued). "The expression and rapid release of NRG1 in neurons and their axons can be stimulated by NGF, BDNF, NT-3, and GDNF, which are extremely abundant in tumor microenvironment." (PMID 36900158, 2023). "On the other hand, CD271 has been proposed as a marker of tumor-initiating-cells in oral human and murine SCC cells, and CD271 activation by NGF results in a more invasive phenotype, most likely involving Trk-CD271 heterodimer signaling." (PMID 37443031, 2023). "Tumor volume and threshold dose of irradiation damage correlated positively with MCP-1 and VEGF as well as NGF and CX3CL, respectively." (PMID 35596772, 2022). "Mast cells can stimulate tumor cell expansion by releasing cytokines and growth factors, including fibroblast growth factor-2 (FGF-2), nerve growth factor (NGF), platelet-derived growth factor (PDGF), IL-10, and IL-8, into the tumor stroma." (PMID 36430483, 2022). "In brief, NGF, the Brain-Derived Neurotrophic Factor (BDNF), Neutrophin 3 (NTF3) and Neutrophin 4 (NTF4) are the major neurotransmitters secreted by neural and tumour cells in PDAC." (PMID 36497277, 2022). "The CREB expression was more activated in the Mhigh subpopulation, directly affecting the expression of BCL-2, VEGF, NGF, and IGF2 in regulating tumor cell proliferation and survival or metastasis." (PMID 35740540, 2022). "Positive correlations of tumor volume and threshold dose of irradiation damage were found for MCP-1 and VEGF as well as NGF and CX3CL, respectively." (PMID 35596772, 2022). "NGF depletion by anti-NGF antibodies, NGF siRNA, or an antagonist of TRK receptors reduced progression, metastasis, tumor innervation, and prolonged survival in mouse models of PDAC." (PMID 36077804, 2022). "CD44v6 + cells produce NGF and NFT3, which in turn recruit ASCs promoting a paracrine loop that increase the tumor cell aggressiveness." (PMID 34408135, 2021). "Mast cells actively participate in tumor development by producing many proangiogenic factors, such as bFGF, VEGF, IL-8, TNF, TGF-β, and nerve growth factor (NGF)." (PMID 34209508, 2021). "In pancreatic cancer, adrenergic signaling to tumor cells induces the release of NGF and brain-derived neurotrophic factor (BDNF), leading to an increase in nerve density in the tumor region." (PMID 34722510, 2021). "Within the tumor, MCs release angiogenic compounds including IL-8, VEGF, FGF-2, NGF, heparin, tryptase, chymase, and TGF-β." (PMID 31256327, 2020). "Conversely, mediators released by MC such as FGF-2, NGF, PDGF, VEGF, IL-8, and IL-10 promote the expansion of tumor cells." (PMID 31256327, 2020). "So, the purpose of this study was to understand better the mechanisms by which metformin blocks NGF-dependent effects in EOC cells and thereby contributes to clarifying the anti-tumour mechanisms of this drug." (PMID 33081077, 2020). "The growth of nerves in cancer is stimulated by the release of neurotrophic growth factors, such as nerve growth factor (NGF) from cancer cells, resulting in an increased nerve density in the tumour microenvironment." (PMID 32001748, 2020). "Mast cell- and macrophage-derived growth factors that can promote tumor development and angiogenesis include TNF-α, TGF-β1, FGF-2, VEGF, platelet-derived growth factor (PDGF), IL-8, osteopontin, and nerve growth factor (NGF)." (PMID 32508920, 2020). "It has been found that NGF can activate PI3K/AKT pathway through phosphorylating AKT in SACC, thereby potentially stimulating scattering and migration of tumor cells which enhances the progression of PNI." (PMID 33014792, 2020). "In turn, the NGF released in the TME promotes nerve growth and further Ach release in a feedback loop sustaining tumor growth and metastasis." (PMID 31812953, 2019). "In HNSCC tumor specimens and in UPPP controls, NGF mRNA was detected by RT-PCR and ISH in epithelial cells including basal cells of normal squamous cell epithelium and malignant tumor cells in cancer cell nests." (PMID 29904026, 2018).
tumor (continued). "The normal epithelium of UPPP, HNSCC tumor cell lines and HNSCC tissue samples expressed various levels of NGF mRNA." (PMID 29904026, 2018). "Small interfering RNA against NGF or proNGF, anti-NGF antibodies, and inhibitors of NGFR were pro-apoptotic and anti-proliferative for cancer cells and inhibited tumor growth and invasiveness." (PMID 28679437, 2017). "The expression levels of the nociceptive mediators NGF and BDNF were higher than those in the tumor cell line bmMDA under acidosis, and of cells of neuronal origin at pH 7.4." (PMID 28903357, 2017). "In GNC–siRNA-treated tumours, 5′-RACE analysis using human NGF gene-specific primers identified a PCR product of expected cleavage product with a molecular weight ∼370 bp." (PMID 28440296, 2017). "Regarding the hypothesis of a favorable link between expression of NGF/NGF-receptors and tumor cell proliferation, it should be taken into consideration that the presence and/or release of “well established” pro-oncogenic molecules might precede the presence of NGF." (PMID 27439311, 2016). "Subsequent analyses of immunohistochemically labelled NGF, BDNF, TrkA, and TrkB proteins in a set of seven tumor samples from seven patients with ES revealed heterogenous expression of these proteins across tumor samples." (PMID 27145455, 2016). "Nerve growth factor (NGF)/nerve growth factor receptors (NGFRs) axis and canonical WNT/β-catenin pathway have shown to play crucial roles in tumor initiation, progression and prognosis." (PMID 27835587, 2016). "To better understand the relationship between tumour microenvironment parameters and cell invasion, we studied the effects of HGF, EGF, IGF, netrin, PDGF-B, TNF-α, bFGF, IL-6, NGF, TGF-β and PlGF-1 in the 3D environment." (PMID 26486848, 2015). "Although the role of HO1 in tumorigenesis remains controversial, recent evidence suggests NGF and HO1 as tumor-progressing factors." (PMID 24180625, 2013). "MCs can exert pro-tumorigenic effects by secreting factors like VEGF and IL-8 that promote tumor angiogenesis, tumor growth factors (i.e., PDGF, NGF, SCF) and proteases that facilitate metastases." (PMID 23950747, 2013). "The specific effects of the various factors secreted by them (such as GDNF, NGF, chemokines, etc.)in different tumor types and microenvironments have not been clearly identified." (PMID 41583906, 2026). "Similar to the process by which tumor cells induce angiogenesis by secreting vascular endothelial growth factor (VEGF) family factors, they can also secrete neurotrophic factors, including BDNF, NGF, NTF3, and NTF4." (PMID 41556039, 2026). "Therefore, targeting neurotrophic signals such as NGF, BDNF, and their respective receptors offers a promising strategy to disrupt tumor adaptive responses." (PMID 41163091, 2025). "While tumour-directed benefits have not been established, these agents illustrate the feasibility of systemic NGF sequestration in humans and, if repurposed for oncology, would warrant careful dose selection and musculoskeletal monitoring." (PMID 41567220, 2025). "Furthermore, in a mouse model of PDAC, catecholamines promoted tumor development dependent on the activation of the ADRB2 receptor and NGF secretion, which was reverted by blocking ADRB2 and the NGF receptor." (PMID 40243726, 2025). "Neurotrophic factors (e.g., NGF, BDNF, GDNF) and axon guidance molecules (e.g., semaphorins, netrins, ephrins) mediate this integration, promoting neural remodeling and facilitating tumor innervation." (PMID 41009819, 2025). "TrkA, a high-affinity receptor for NGF, regulates various downstream signaling pathways, such as RAS/MAPK, PI3K/AKT, and PLCγ, which promote cell proliferation, differentiation, survival, and tumor vascularization." (PMID 39860039, 2025). "Notably, NGF and BDNF are upregulated across multiple cancers, including OS, where they correlate with enhanced tumour innervation, disease progression, and poor outcome." (PMID 41029717, 2025).